TREM2 (triggering receptor expressed on myeloid cells 2)
Description:
Forms a receptor signaling complex with TYROBP which mediates signaling and cell activation following ligand binding. Acts as a receptor for amyloid-beta protein 42, a cleavage product of the amyloid-beta precursor protein APP, and mediates its uptake and degradation by microglia. Binding to amyloid-beta 42 mediates microglial activation, proliferation, migration, apoptosis and expression of pro-inflammatory cytokines, such as IL6R and CCL3, and the anti-inflammatory cytokine ARG1 (By similarity). Acts as a receptor for lipoprotein particles such as LDL, VLDL, and HDL and for apolipoproteins such as APOA1, APOA2, APOB, APOE, APOE2, APOE3, APOE4, and CLU and enhances their uptake in microglia. Binds phospholipids (preferably anionic lipids) such as phosphatidylserine, phosphatidylethanolamine, phosphatidylglycerol and sphingomyelin. Regulates microglial proliferation by acting as an upstream regulator of the Wnt/beta-catenin signaling cascade (By similarity). Required for microglial phagocytosis of apoptotic neurons. Also required for microglial activation and phagocytosis of myelin debris after neuronal injury and of neuronal synapses during synapse elimination in the developing brain (By similarity). Regulates microglial chemotaxis and process outgrowth, and also the microglial response to oxidative stress and lipopolysaccharide (By similarity). It suppresses PI3K and NF-kappa-B signaling in response to lipopolysaccharide; thus promoting phagocytosis, suppressing pro-inflammatory cytokine and nitric oxide production, inhibiting apoptosis and increasing expression of IL10 and TGFB (By similarity). During oxidative stress, it promotes anti-apoptotic NF-kappa-B signaling and ERK signaling (By similarity). Plays a role in microglial MTOR activation and metabolism (By similarity). Regulates age-related changes in microglial numbers. Triggers activation of the immune responses in macrophages and dendritic cells. Mediates cytokine-induced formation of multinucleated giant cells which are formed by the fusion of macrophages (By similarity). In dendritic cells, receptor of SEMA6D with PLEXNA1 as coreceptor and mediates up-regulation of chemokine receptor CCR7 and dendritic cell maturation and survival. Involved in the positive regulation of osteoclast differentiation.
Synonyms: TREM-2; Trem2a; Trem2b; Trem2c; AD17; PLOSL2
Tractability: Small molecule: a structure with a bound ligand is known. Antibody: UniProt places it where antibodies can reach, with high confidence; its Gene Ontology location is reachable by antibodies, with high confidence; UniProt predicts a signal peptide or a membrane-spanning region.
Gene: Protein-coding gene on chromosome 6 (41,158,488 to 41,163,186, reverse strand). Ensembl gene ENSG00000095970.
Subcellular location: Cell membrane (Isoform 1); Secreted (Isoform 2); Secreted (Isoform 3)
Subcellular location (Human Protein Atlas): Vesicles; Predicted to be secreted
Pathways (Reactome):
Immune System: DAP12 interactions; DAP12 signaling; Immunoregulatory interactions between a Lymphoid and a non-Lymphoid cell
Developmental Biology: Other semaphorin interactions
Gene Ontology:
Molecular function: amyloid-beta binding; apolipoprotein A-I binding; apolipoprotein binding; beta-catenin binding; high-density lipoprotein particle binding; kinase activator activity; lipoprotein particle binding; low-density lipoprotein particle binding; phosphatidylethanolamine binding; phosphatidylserine binding; phospholipid binding; protein binding; protein-containing complex binding; scaffold protein binding; semaphorin receptor activity; signaling receptor activity; sulfatide binding; transmembrane signaling receptor activity; very-low-density lipoprotein particle binding; lipid binding; protein tyrosine kinase binding; carbohydrate derivative binding; lipopolysaccharide binding; lipoteichoic acid binding; peptidoglycan binding; and 1 more
Biological process: amyloid-beta clearance; amyloid-beta clearance by cellular catabolic process; cellular response to lipid; cellular response to lipoprotein particle stimulus; cellular response to oxidised low-density lipoprotein particle stimulus; CXCL12-activated CXCR4 signaling pathway; dendritic cell differentiation; memory; negative regulation of macrophage colony-stimulating factor signaling pathway; negative regulation of neuroinflammatory response; negative regulation of NLRP3 inflammasome complex assembly; negative regulation of phosphatidylinositol 3-kinase/protein kinase B signal transduction; osteoclast differentiation; phagocytosis, recognition; positive regulation of amyloid-beta clearance; positive regulation of antigen processing and presentation of peptide antigen via MHC class II; positive regulation of C-C chemokine receptor CCR7 signaling pathway; positive regulation of calcium-mediated signaling; positive regulation of CD40 signaling pathway; positive regulation of engulfment of apoptotic cell; positive regulation of ERK1 and ERK2 cascade; positive regulation of gene expression; positive regulation of intracellular signal transduction; positive regulation of microglial cell activation; positive regulation of microglial cell migration; and 84 more
Cellular component: membrane; plasma membrane; plasma membrane raft; semaphorin receptor complex; extracellular region
Genetic constraint (gnomAD): Loss-of-function variants: 21 observed, 24.97 expected, observed/expected ratio (o/e) 0.84, 90% interval 0.6 to 1.21. The upper end of that interval is the gene's LOEUF score, 1.21, which puts it in group 5 of 6, group 1 being the genes least tolerant of losing a copy. Missense variants: 267 observed, 303.25 expected, observed/expected ratio (o/e) 0.88, 90% interval 0.8 to 0.97. Synonymous variants: 111 observed, 127.68 expected, observed/expected ratio (o/e) 0.87, 90% interval 0.74 to 1.02.
Homologues: Orthologues: chimpanzee TREM2 (99% identical), macaque TREM2 (97% identical), pig TREM2 (69% identical), mouse Trem2 (68% identical), guinea pig TREM2 (68% identical), rat Trem2 (60% identical). Paralogues in human: CD300E (21% identical), CD300A (21% identical), CD300H (20% identical), CD300LG (20% identical), CD300C (20% identical), CD300LB (20% identical), TREML1 (20% identical), CD300LF (19% identical), CD300LD (18% identical), FCMR (17% identical), PIGR (16% identical), FCAMR (15% identical), and 1 more.
Diseases named in the same sentence as TREM2 in open-access papers:
TREM2 is named in the same sentence as 351 diseases in open-access papers, as found by Europe PMC text mining. Sharing a sentence is not in itself a finding about the gene and the disease. The quoted sentences say what the papers report.
Alzheimer disease (503 papers, 2013 to 2026). A progressive, neurodegenerative disease characterized by loss of function and death of nerve cells in several areas of the brain leading to loss of cognitive function such as memory and language. "A TREM2 gene variant known as TREM2-R47H is associated with an increased risk of developing Alzheimer's disease (AD)." (PMID 41890852, 2026). "Triggering receptor expressed on myeloid cells 2 (TREM2) is a central regulator of microglial activity and loss-of-function coding variants are major risk factors for late onset Alzheimer's disease (LOAD)." (PMID 41580393, 2026). "We evaluated InCytokine by profiling wild-type microglia, TREM2 knockout, and Alzheimer's disease-associated TREM2 R47H variant cells in response to lipopolysaccharide and sulfatide exposure." (PMID 41683566, 2026). "TREM2 plays multiple functional roles in microglia and variants are associated with increased risks of Alzheimer's disease (AD)." (PMID 42298074, 2026). "For example, in Alzheimer's disease (AD), numerous rare variants have been identified that are significantly associated with disease risk, including TREM2, ABCA7, and SORL1." (PMID 41482638, 2026). "Hypomorphic variants in the TREM2 gene significantly increase the risk of developing Alzheimer’s disease (AD)." (PMID 41585038, 2026). "YKL-40 and TREM2 track astrocytic and microglial activation respectively and have been associated with disease stage in Alzheimer’s disease." (PMID 41583439, 2025). "Mutations in the TREM2 gene have been linked to various neurodegenerative diseases, including Alzheimer’s disease (AD), frontotemporal dementia (FTD), Parkinson’s disease (PD), and Nasu–Hakola disease (NHD)." (PMID 40806186, 2025). "Individuals heterozygous for rare inactivating variants of TREM2, notably the R47H mutation, are at increased risk of developing Alzheimer’s disease (AD)." (PMID 40400621, 2025). "Variants in TREM2 have been implicated as genetic risk factorsfor Alzheimer’s disease (AD), most notably the extracellulardomain variant R47H." (PMID 41298271, 2025). "The Alzheimer's disease-associated genetic variant TREM2 R47H, which modulates ligand binding, has also been implicated in ALS, supporting the importance of correctly functioning lipid metabolism in microglia." (PMID 41333389, 2025). "UB-BJ02 also modulated Alzheimer’s disease risk molecules by decreasing the expression of triggering receptor expressed on myeloid cells 2 (TREM2) and increasing cluster of differentiation 33 (CD33)." (PMID 41007636, 2025). "Previous research has indicated that deficiency of TREM2 augments the accumulation of amyloid β and neuronal loss in a mouse model of Alzheimer’s disease." (PMID 40424233, 2025). "The TREM2 His157Tyr variant is associated with an increased risk of Alzheimer’s disease, particularly in the Han Chinese population." (PMID 40806186, 2025). "For instance, TREM2 is implicated in the deposition of Alzheimer's disease-associated Aβ plaques and tau proteins, thereby modulating the neurodegenerative process through the clearance of these pathological entities." (PMID 40552184, 2025). "TREM2 mutation has been identified as a risk factor for Alzheimer’s disease (AD) and other neurodegenerative diseases (NDD)." (PMID 41000074, 2025). "The R47H variant of the triggering receptor expressed on myeloid cells 2 (TREM2) is a risk factor for Alzheimer’s disease in humans and leads to lower bone mass accrual in female but not male 12-mo-old mice." (PMID 39677924, 2025). "These TREM2 variants also give the highest risk of Alzheimer’s disease among any risk factors found in recent 20 years." (PMID 41000074, 2025). "The R47H missense mutation of the TREM2 gene is a known risk factor for development of Alzheimer’s Disease." (PMID 39103533, 2025).
Alzheimer disease (continued). "Rare heterozygous coding variants in TREM2 (for example p.R47H) confer a substantial increase in risk of late-onset Alzheimer’s disease, as shown independently by two large case–control sequencing studies in 2013." (PMID 41454181, 2025). "TREM2, a myeloid receptor transmitting intracellular signals that sustain microglial responses during Alzheimer's disease, has recently gained attention for its association with tumor progression and immune response 24-26." (PMID 39744236, 2025). "Recently, the importance of TREM-2 has been highlighted by the identification of coding variants, such as the TREM2-R47H form, that increase risk for Alzheimer’s disease." (PMID 40948752, 2025). "One key discovery identified in the TREM2 (Triggering receptor expressed on myeloid cell 2) gene is the R47H missense variant, a strong risk factor for development of Late-Onset Alzheimer’s Disease (LOAD)." (PMID 39103533, 2025). "Variants in the triggering receptor expressed on myeloid cells (TREM2) are linked to an increased risk of developing dementia, including late‐onset Alzheimer's disease (AD)." (PMID 39726135, 2025). "Variants of the gene “triggering receptor expressed on myeloid cells 2” (TREM2) are major genetic risk factors for late-onset Alzheimer’s disease, frontotemporal lobar degeneration, and the Nasu–Hakola disease." (PMID 40081988, 2025). "Among these proteins is the Alzheimer’s disease-associated TREM2, which is an uncommon substrate due to a charged lysine residue in its TMD44." (PMID 40593564, 2025). "Variants in the triggering receptor expressed on myeloid cells 2 (TREM2) gene have been demonstrated to increase the risk of late-onset Alzheimer’s disease (AD) and Nasu-Hakola disease." (PMID 41168805, 2025). "Particularly, TREML-1 can enhance the calcium signalling in an SHP2 (PTPN11)-dependent manner, whereas some genetic variant of TREML-2 have been identified to be protective for Alzheimer’s disease, contrary to TREM-2 genetic variants." (PMID 40948752, 2025). "Polymorphisms in the TREM2 gene are major risk factors for neurodegenerative disorders like Alzheimer’s disease." (PMID 40028337, 2025). "Subsequently, rare variants located within exon 2 of TREM2, including rs75932628 (R47H) and rs143332484 (R62H), have been reported to increase the risk of developing Alzheimer’s disease (AD)." (PMID 41300781, 2025). "The TREM2 Arg62His (rs143332484) variant was first reported in a European American cohort and was revealed to be a strong Alzheimer’s disease (AD) risk factor." (PMID 40806186, 2025). "Genomic and transcriptomic approaches reveal disease-specific risk genes (e.g., TREM2 in Alzheimer’s disease, ATXN2 in ALS) and biomarkers, enabling more precise diagnosis and personalized medicine." (PMID 40805906, 2025). "The Alzheimer’s disease risk gene Triggering Receptor Expressed on Myeloid cells 2 (TREM2) is a key regulator of this activation state." (PMID 41278975, 2025). "Aberrant DNA methylation has been observed in genes linked to neurodegeneration, including APP, PSEN1, and TREM2 in Alzheimer’s disease (AD), as well as SNCA and LRRK2 in Parkinson’s disease (PD)." (PMID 40076852, 2025). "The cell surface receptor TREM2 is a key genetic risk factor and drug target in Alzheimer’s disease (AD)." (PMID 40081988, 2025). "Emerging clinical and preclinical evidence underscores the potential of TREM2 and sTREM2 as diagnostic biomarkers and therapeutic targets in Alzheimer’s disease (AD)." (PMID 40247363, 2025). "Mutations in TREM2 represent a high-impact risk factor for Alzheimer's disease (AD) which turned TREM2 into a significant drug target." (PMID 40325411, 2025). "TREM2 (Triggering receptor expressed on myeloid cells 2) is a microglial surface protein, where variants like R47H increase Alzheimer's disease (AD) risk by approximately threefold." (PMID 41585268, 2025). "TREM2 has been verified as a risk factor for Alzheimer’s disease (AD), especially late-onset AD (LOAD)." (PMID 40806186, 2025).
Alzheimer disease (continued). "TREM2 variants R47H and R62H have been associated with Alzheimer's disease, yet the underlying mechanisms remain elusive." (PMID 39159814, 2024). "Mutations in the TREM2 gene have been associated with an increased risk of developing late-onset Alzheimer’s disease, probably through a reduced microglial ability to clear Aβ, impairing the inflammatory response." (PMID 39596011, 2024). "Trem2 has been implicated in various pathological contexts, including early-onset Alzheimer’s disease, where Trem2 facilitates the clearance of amyloid-β peptide." (PMID 38869957, 2024). "Lastly, microglia express and release Apolipoprotein E (ApoE), a putative TREM2 agonist, and polymorphisms in the Apoe gene are a major risk determinate of Alzheimer’s disease." (PMID 38247852, 2024). "A large body of literature has demonstrated a strong association of certain Trem2 alleles with Alzheimer's disease and related dementias." (PMID 38825965, 2024). "We also found a substantial overlap to genes defined in the “Disease associated microglia” and TREM2 activated pathways detected in animal models of Alzheimer disease." (PMID 38195627, 2024). "Homozygous loss-of-function mutations in TREM2 seem to be a vital risk factor for late-onset Alzheimer’s disease, and a significant association has been reported between TREM2 and Parkinson’s disease, amyotrophic lateral sclerosis, and frontotemporal dementia." (PMID 39544929, 2024). "Multiple studies have consistently linked polymorphic variants of TREM2 to late-onset Alzheimer's disease." (PMID 39113887, 2024). "TREM2 mutations or dysregulation of TREM2 signaling are associated with the risk of neurodegenerative diseases, such as Alzheimer’s disease." (PMID 38392305, 2024). "Mutations in TREM2 are linked to several neurodegenerative diseases including Alzheimer’s disease (AD)." (PMID 38392305, 2024). "Several independent genome-wide sequencing studies further showed that individuals with the H157Y mutation, the rare R47H mutation, and the R62H mutation in Trem2 gene, which impair binding to phospholipid ligands, are susceptible to Alzheimer disease (AD)." (PMID 38236825, 2024). "Loss of Trem2 function triggers a chronic inflammatory response that exacerbates Alzheimer’s disease." (PMID 38348100, 2024). "Soluble triggering receptor expressed on myeloid cells 2 (sTREM2) is a potential neuroinflammatory biomarker linked to the pathogenesis of Alzheimer’s disease (AD) and mild cognitive impairment (MCI)." (PMID 38841103, 2024). "Carriers of certain TREM2 gene variants (R47H, D87N, L211P, H157Y, R62H, and T96K) have an increased risk of Alzheimer’s disease (AD)." (PMID 37489359, 2023). "Genetic variation in the TREM2 gene has been implicated in risk for Alzheimer’s disease and frontotemporal dementia, while homozygous TREM2 mutations cause a rare leukodystrophy, Nasu-Hakola disease (NHD)." (PMID 37115208, 2023). "This has become an increasingly pressing challenge as rare variants in TREM2 have been identified as risk factors in Alzheimer’s disease and frontotemporal dementia." (PMID 37115208, 2023). "The R47H mutation in Trem2 is one of the strongest genetic risk factors of late-onset Alzheimer’s disease (LOAD)." (PMID 37016304, 2023). "Elevated levels of TREM2 in cerebrospinal fluid have been associated with increased amyloid plaque burden, neurodegeneration, and cognitive decline in individuals with Alzheimer’s disease." (PMID 37569296, 2023). "Triggering receptor expressed on myeloid cells 2 (TREM2), a pattern recognition receptor abundantly expressed on microglia, has been identified as one of the risk factors for Alzheimer’s disease (AD)." (PMID 38020891, 2023). "Elevated TREM2 levels in these cells are associated with age-related pathological conditions, including Alzheimer’s disease." (PMID 37291187, 2023). "TREM2 is expressed mainly in macrophages and in microglia, and its polymorphisms are strongly linked to the risk of Alzheimer’s disease." (PMID 37108808, 2023).